ADAM10 (ADAM metallopeptidase domain 10)
Diseases named in the same sentence as ADAM10 in open-access papers (continued):
Sharing a sentence is not in itself a finding about the gene and the disease.
melanoma (continued). "We next verified whether ADAM10 is involved in immune-escape of melanoma cells." (PMID 39837817, 2025). "Thus, ADAM10 might act as a crossroad in the hormonal control of immunosurveillance and invasion of melanoma cells." (PMID 39837817, 2025). "Moreover, PTP4A3 correlated with the expression of several proteases like ADAM10 (A Disintegrin and Metalloproteinase 10), which is upregulated in melanoma metastases and related to many adhesion molecules that have a central role in developing malignant melanoma." (PMID 35480119, 2022). "Notably, a high percentage of melanoma cells are positive for ADAM10, suggesting that it may regulate the immune response during the onset and progression of melanoma." (PMID 33789714, 2021). "The central role of MITF in melanoma biology as well as in shaping the immune response means that approaches combining inhibition of ADAM10 with manipulation of MITF levels, for example to sensitize cells to therapy, may provide an avenue towards more effective immune therapy." (PMID 33789714, 2021). "In addition, the migration of melanoma cells was induced by overexpression of ADAM10." (PMID 25333745, 2015). "It must be stressed that it is a hypothesis that needs to be supplemented and validated empirically with a much larger study group and animal models of metastasis; however, it is a voice in the discussion and confirms the hypotheses concerning the role of ADAM-10 in melanoma progression." (PMID 26266086, 2015). "Of the nine putative proteomic biomarkers studied in an independent cohort using IHC, CDK4, ADAM10, SCAI, and DDX11 seem promising starting points for further investigation of their role in melanoma routine diagnostics." (PMID 40075679, 2025). "We found that ADAM10 and SCAI expression was increased in the primary melanomas from patients with OS > 5 years compared to tumors from patients with OS < 5 years (Mann-Whitney U test p-value < 0.05)." (PMID 40075679, 2025). "Specific blockade of ADAM10 or androgen receptor impairs the androgen-induced MICA shedding and melanoma immune-escape." (PMID 39837817, 2025). "In supporting this, it was shown that ADAM10 and CD44 were found to be colocalized at the ruffling membrane structures in human melanoma cells." (PMID 34796172, 2021). "To gain further insight in the regulation of ADAM10 by MITF, we established human IGR37 melanoma cells in which MITF was knocked out using CRISPR/Cas9." (PMID 33789714, 2021). "Studies found that ADAM10 promoted cell migration via regulating modulation of CD44 in the pituitary adenoma cell and melanoma cell." (PMID 32256208, 2020). "Statistical analysis revealed a significant correlation between enhanced immunoreactivity of ADAM-10 and augmented expression of N-cadherin and SPARC in primary tumor cells and melanoma cells in nodal metastases." (PMID 26266086, 2015). "Moreover, we also revealed a significant correlation between enhanced immunoreactivity of ADAM-10 and augmented expression of N-cadherin and SPARC in primary tumor cells and melanoma cells in nodal metastases which may be associated with the potential role of ADAM-10 in the process of EMT." (PMID 26266086, 2015). "The shedding of EGFR ligands is mainly dependent on the metalloproteases ADAM-17 and ADAM10, the latter being induced by PAX2 in melanoma." (PMID 24970815, 2014). "In our previous study we demonstrated that ADAM10 is involved in the shedding of L1-CAM, a neural cell adhesion molecule known to be overexpressed in different types of cancer including melanoma." (PMID 21876729, 2011). "Nonetheless, our study provides the first evidence of a direct relationship between androgens and MICA/B shedding by ADAM10 in melanoma, which is classically considered a ‘non-hormone dependent cancer’." (PMID 39837817, 2025).
melanoma (continued). "It was shown that ADAM10 or ADAM17-mediated cleavage of CD44 is triggered upon different stimulation e.g., by Ca2+ influx or protein kinase C (PKC) activation, whereas a study on melanoma cells indicated that constitutive and endogenous shedding of CD44 is mediated by ADAM10." (PMID 36876041, 2023). "Unlike irradiated parental B16/F10 melanoma cells which form lung tumors in nude mice but not in immunocompetent mice owing to T-cell-mediated immune rejection, the ADAM10-KO cells behave like MITF-KO cells in that they fail to form tumors in nude mice." (PMID 33789714, 2021). "Analysis of the normalized expression data from the 479 samples in TCGA melanoma cohort (RNA-seq) showed a clear positive correlation between the expression of MITF and ADAM10 with a Spearman coefficient of 0.34 (p = 1.44e− 14) and a Pearson coefficient of 0.37 (p = 6.57e− 17)." (PMID 33789714, 2021). "In this context, inhibiting ADAM10 activity, but maintaining MITF transcriptional function could represents a rational strategy to guide melanoma cells to their destruction by the immune system." (PMID 33789714, 2021). "Since TACE/ADAM17 and ADAM10 were shown previously to play an important role in ligand and receptor shedding, we analyzed A375 and SK Mel 28 melanoma cells and found that they expressed ADAM10 but not TACE/ADAM17." (PMID 33327495, 2020). "ADAM10 is regulated by transcription factor PAX2 in renal cell carcinoma and melanoma cells." (PMID 30117015, 2018). "Importantly, we present strong evidence, that PAX2 can regulate ADAM10 expression and that the downregulation of PAX2 inhibits the anchorage independent cell growth of melanoma cells." (PMID 21876729, 2011). "The identification of ADAM10 as an MITF target gene, suggests that MITF may play a dual role in shaping the anti-melanoma immune response, both promoting expression of antigens like MLANA known to elicit a robust T-cell response, but at the same time suppressing NK-cell-mediated killing." (PMID 33789714, 2021). "Only the melanoma cell line NW1539 expressed neither PAX2 nor ADAM10." (PMID 21876729, 2011). "In human melanoma cells, constitutive shedding of CD44 was reported to be mediated by ADAM10 but not by MT1-MMP or ADAM17 despite all of these enzymes were expressed in the cells." (PMID 34796172, 2021).
neuroblastoma (22 papers, 2009 to 2024). Neuroblastoma (NB) is the most common solid, extracranial childhood tumor. "The ability of the soluble ADAM10 to shed overexpressed and endogenous APP was determined with an ADAM10 knockout cell line and a human neuroblastoma cell line, respectively." (PMID 37266401, 2023). "In another study, it has been indicated that miR-144 and miR-451 regulate the expression of ADAM10 in HeLa and human neuroblastoma SH-SY5Y cells." (PMID 36918870, 2023). "In this regard, it has been shown that statins increase APP processing leading to generate sAPPα in N2a mouse neuroblastoma cells through an isoprenoid-mediated mechanism, and possibly ADAM10 induction." (PMID 36918870, 2023). "In SH-SY5Y neuroblastoma cells, ADAM10 achieves its major protease activity in the fraction obtained from plasma membrane lysis, where the mature form of the enzyme is detected, confirming the importance of ADAM10 localization for its activity." (PMID 33670873, 2021). "ADAM10 activity was evaluated in different biological materials (CSF, plasma, SH-5YSY neuroblastoma cells, and platelets)." (PMID 33670873, 2021). "In another study 50% hypoxia decreased ADAM-10 protein expression in human neuroblastoma tissue culture." (PMID 31487291, 2019). "The retinoic acid receptor analog acitretin, which up-regulates ADAM10, also promoted PrPC shedding and decreased AβO binding in the neuroblastoma cells and in human induced pluripotent stem cell (iPSC)-derived cortical neurons." (PMID 30872401, 2019). "Here, we have used human neuroblastoma cells and iPSC-derived cortical neurons to show that carbachol and acitretin promote the shedding of cell surface PrPC through activation of ADAM10." (PMID 30872401, 2019). "We have shown that activation of ADAM10 promotes the proteolytic shedding of the AβO receptor PrPC from the surface of human neuroblastoma cells and iPSC-derived neurons." (PMID 30872401, 2019). "We therefore used primary porcine brain endothelial cells (PBECs) and human neuroblastoma cells (SH-SY5Y) transfected with an ADAM10-promoter luciferase reporter vector in an indirect co-culture system." (PMID 24608847, 2014). "For this purpose, we co-cultured porcine brain endothelial cells (PBECs) on filter membranes and human neuroblastoma cells (SH-SY5Y) transfected with an ADAM10-promoter-driven reporter gene, seeded on the bottom of the basal well." (PMID 24608847, 2014). "Endogenous ADAM10 mRNA levels and the ADAM10 promoter activities were increased on RA treatment in neuroblastoma cells: thus, retinoic acid works as an activator of the α-secretase." (PMID 19519313, 2009). "On the other hand, ADAM10 was active in platelets and neuroblastoma cells." (PMID 33670873, 2021). "Therefore, we performed high-throughput small-molecule screening in SH-SY5Y (human neuroblastoma) cells that stably express a luciferase reporter gene driven by the ADAM10 promoter, including a portion of its 5’-untranslated region (5’UTR)." (PMID 29942252, 2018). "Here, we found that in human neuroblastoma cells, activation of ADAM10 with the muscarinic agonist carbachol promotes PrPC shedding and reduces the binding of AβO to the cell surface, which could be blocked with an ADAM10 inhibitor." (PMID 30872401, 2019). "In neuroblastoma N2a cells expressing human APP Swedish mutant, overexpression of the SIRT1 gene increased ADAM10 protein expression." (PMID 27532339, 2016). "TDE-expressed NKG2D ligands, including the major histocompatibility complex class I polypeptide-related sequence A and B (MICA/B) and a disintegrin and metalloproteinase domain-containing protein 10 (ADAM10), are also considered as the “pseudoligands” to neutralize NKG2D in neuroblastoma." (PMID 36359776, 2022). "Additionally, we found that expression of the long noncoding RNA MALAT1 was significantly increased in senescent neuroblastoma cells, and that MALAT1 served as a sponge for microRNA (miR)-92a-3p to counteract miR-92a-3p-mediated repression of ADAM10 levels." (PMID 35309907, 2022).
neuroblastoma (continued). "The increased catalytic activity of ADAM10 and Sox2 expression is in conjunction with gamma (γ)-secretase inhibition, suggesting an antagonistic relationship between Sox2 and γ-secretase activity, demonstrated in both HEX 293 and human neuroblastoma SH-SY5Y cells lines." (PMID 39336125, 2024). "In addition, recent findings of our group have demonstrated that in plasma and CSF samples of both healthy and AD patients, ADAM10 is unable to cleave a fluorogenic substrate, whereas in whole lysates of platelets and SH-SY5Y neuroblastoma cells, the protein is active." (PMID 33419480, 2021). "The data suggest that ALC did not alter the level of ADAM10 protein, but rather influenced the delivery of ADAM10 to the post-synaptic compartment, and consequently positively modulated its enzymatic activity towards APP in neuroblastoma cells." (PMID 29382156, 2018). "As with surface expression of ADAM10, generation of the ADAM10 CTF was not affected by carbachol, in contrast with an earlier report that PMA increases ADAM10 shedding in SH-SY5Y neuroblastoma cells." (PMID 21586144, 2011).
gastric cancer (20 papers, 2013 to 2025). A primary or metastatic malignant neoplasm involving the stomach. "ADAM10 is similarly elevated in other GI cancers, including gastric cancer, where higher ADAM10 levels are also linked to invasion, metastasis, and a poor prognosis." (PMID 40427200, 2025). "Erythropoietin-producing hepatocellular (Eph) receptor type A8 (EphA8) expression was associated with poor prognosis of patients with gastric cancer, and its knockdown decreased the expression of ADAM10, indicating that EphA8 is an upstream regulator of ADAM1052." (PMID 39755747, 2025). "We believe that ADAM12, ADAM17 mRNA and ADAM10 protein are worth further investigation as biomarkers for gastric cancer screening, and that players in the ADAM-NKG2D axis are worth investigation for cancer diagnostics and therapeutics." (PMID 39755747, 2025). "The expression levels of miR-448 and miR-320a were negatively correlated with those of ADAM10 in gastric cancer tissues, and overexpression of these miRNAs suppressed gastric cancer cell proliferation, colony formation, and invasion." (PMID 39755747, 2025). "Above studies support that ADAM12, ADAM17 and ADAM10 hold potential as biomarkers for gastric cancer." (PMID 39755747, 2025). "Another report indicates a relationship between ADAM10 in gastric cancer and worsened prognosis through a positive correlation with tumor size, infiltration depth, vascular invasion, lymph node involvement or the presence of distant metastases." (PMID 36286024, 2022). "Univariate and multivariate analysis results of variables including ADAM10 expression affecting cumulative survival in patients undergoing curative surgery for gastric cancer." (PMID 33679947, 2021). "ADAM10, a member of the ADAM (a disintegrin and metalloproteinase) family has also been found to be associated with gastric carcinoma and has been suggested as a potential therapeutic target." (PMID 33679947, 2021). "The progression of gastric cancer correlates with the expression of ADAM10 and ADAM17 and high ADAM10/ADAM17 expression levels were associated with patient’s poor prognosis and the establishment of lymph node metastasis." (PMID 32698506, 2020). "ADAM expression has been described to be upregulated in individuals with H. pylori gastritis (ADAM-10, -17, -19) and gastric cancer (ADAM-9, -10, -12, -15, -17, -19, -20)." (PMID 28398251, 2017). "In gastric cancer the expression of ADAM10, ADAM15, ADAM17 and ADAM 20 transcripts is markedly increased." (PMID 25437333, 2013). "Micro RNAs are also involved in gastric cancer development by influencing ADAM10 or ADAM17." (PMID 39755747, 2025). "MiR-320a can inhibit cell growth and chemosensitivity through regulating ADAM10 in gastric cancer." (PMID 35799265, 2022). "The authors have suggested that potential therapeutic strategies for gastric carcinoma may be based on the miR-320a/ADAM10 axis." (PMID 33679947, 2021). "Moreover, in gastric cancer cells, ADAM10 and ADAM17 are pulled down together by RECK - suggesting a physical interaction between RECK and ADAMs at the cell surface." (PMID 25246708, 2014). "Compared to ADAM10 and ADAM17, the role of ADAM12 in relation to gastric cancer development is relatively less studied." (PMID 39755747, 2025). "When gastric cancer tissue was paired with normal tissue from the same patient with gastric cancer (n = 32), ADAM8, ADAM9, ADAM10, ADAM12, and ADAM17 mRNAs showed significantly higher expression in gastric cancer tissues (p < 0.05)." (PMID 39755747, 2025). "In the current study, we identified ADAM10, ADAM12 and ADAM17 simultaneously as potential biomarkers for gastric cancer diagnosis." (PMID 39755747, 2025). "There are other ways in which ADAM10 and ADAM17 participate in gastric cancer development via various signaling pathways." (PMID 39755747, 2025). "Gastric cancer tissues (n = 415) expressed significantly higher mRNA levels of ADAM8, ADAM9, ADAM10, ADAM12, and ADAM17 (p < 0.001) than normal tissues (n = 35)." (PMID 39755747, 2025).
gastric cancer (continued). "TSPAN5 has been shown to interact with ADAM10 and act as an oncogene in HCC and a tumor suppressor gene in gastric cancer." (PMID 37047447, 2023). "The ADAM10 and ADAM17 proteins seem to play a particularly significant role in the pathogenesis of gastric cancer." (PMID 37185715, 2023). "As a proof-of-concept pilot study, the expression of ADAM8, ADAM9, ADAM10, ADAM12, ADAM17, and major histocompatibility complex (MHC) class I chain-related sequence A (MICA), a ligand for NKG2D, in gastric cancer was investigated in silico using The Cancer Genome Atlas (TCGA) database." (PMID 39755747, 2025). "In gastric cancer cells, IL-8 induced shedding of EGFR ligands to lead to EGFR transactivation in a pathway that is dependent on ADAM10 but not on ADAM12 or ADAM1753." (PMID 39755747, 2025).